CAMP (cathelicidin antimicrobial peptide)
Diseases named in the same sentence as CAMP in open-access papers (continued):
Sharing a sentence is not in itself a finding about the gene and the disease.
breast carcinoma (continued). "CAMP was significantly increased in breast cancer cells as a result of signaling through ErbB2." (PMID 39351437, 2024). "This direct cytotoxicity prompted us to test whether CAMP is functional in killing the MVT-1 breast cancer cells." (PMID 34298975, 2021). "Here we report the interaction of CAMP with TAMs in breast cancer." (PMID 32365569, 2020). "In addition, breast cancer cells co-cultured with macrophages upregulated CAMP expression and also increased cancer cell viability." (PMID 32365569, 2020). "Additionally, we revealed CAMP was upregulated in breast cancer patients’ plasma when compared with normal individuals." (PMID 32365569, 2020). "Additionally, CAMP knockdown downregulated stemness-related genes, as well as decreased production of oncospheres in SK-BR-3 breast cancer cells." (PMID 32365569, 2020). "CAMP expression was upregulated in cancer tissues and in the circulation of breast cancer patients." (PMID 32365569, 2020). "In view of the intimate relationship between CAMP and TAMs, we focused on the characterization of CAMP in breast cancer and its interaction with TAMs, which remains largely unknown." (PMID 32365569, 2020). "In fact, CAMP overexpression has been shown to suppress tumorigenesis in colon and gastric cancer but also to promote development and progression of ovarian, lung and breast cancer." (PMID 27832772, 2016). "Estrogen receptor (ER)α + breast cancer cells showed the highest basal CAMP gene expression." (PMID 27832772, 2016). "Given that calcitriol, a recognized antineoplastic hormone, is the most known robust inducer of CAMP expression in humans, herein we studied the regulatory actions of this compound upon CAMP expression in vitro and in vivo in different types of breast cancer cells." (PMID 27832772, 2016). "Herein we asked if the well-known antineoplastic hormone calcitriol could differentially modulate CAMP gene expression in human breast cancer cells depending on the cell phenotype in terms of efficacy and potency." (PMID 27832772, 2016). "While additional studies of CAMP effects on breast cancer biology await to be undertaken, the calcitriol-mediated induction of CAMP gene in cancerous tissues has been shown in B-cell lymphomas, acute myeloid leukemia, colon, prostate, endometrial and ovarian cancer cell lines." (PMID 27832772, 2016). "Higher circulating levels of PGLYRP1, CAMP, MMP9 and CEACAM8 prior to and after the first dose of DOX chemotherapy may further contribute to progressive cardiovascular disorders in breast cancer survivors and may potentially predict the risk of both acute subclinical and late cardiotoxicity." (PMID 39273682, 2024). "In our in vivo experiment, the CAMP receptor antagonist indeed attenuated the TAM-associated tumor growth promotion effect, providing evidence that CAMP could serve as a potential target to inhibit breast cancer growth by disrupting the interaction between TAM andcancer cells." (PMID 32365569, 2020). "This study aimed to validate mRNA expression of the previously identified biomarkers of DOX-induced cardiotoxicity, PGLYRP1, CAMP, MMP9, and CEACAM8, and to assay their protein expression in the peripheral blood of breast cancer patients." (PMID 39273682, 2024). "In this study, we evaluated the potential of the neutrophil biomarkers PGLYRP1/TAG7, CAMP/LL37, MMP9, and CEACAM8/CD66b to predict DOX-induced cardiotoxicity in patients with early-stage breast cancer." (PMID 39273682, 2024). "Here, we report that DOX therapy induced increased circulating levels of the neutrophil markers PGLYRP1, CAMP, MMP9, and CEACAM8 early after a single dose of chemotherapy in breast cancer patients." (PMID 39273682, 2024). "The aim of this study was to validate previously determined mRNA biomarkers of DOX-induced presymptomatic cardiotoxicity, PGLYRP1, CAMP, MMP9, and CEACAM8 and to assay their protein expression in breast cancer patients’ circulation." (PMID 39273682, 2024).
breast carcinoma (continued). "PAICS, a key enzyme for de novo purine synthesis, activates the cAmp/PKA signaling pathway, promotes mTOR activity, activates estrogen receptor alpha, and enhances estrogen dependence and tamoxifen resistance in breast cancer." (PMID 39256367, 2024). "In this study we analyzed peripheral blood samples from 40 patients with early-stage breast cancer treated with DOX-based chemotherapy for protein and mRNA expression of PGLYRP1, CAMP, MMP9 and CEACAM8." (PMID 39273682, 2024). "Upregulation of CD163, CAMP, P2X7 in macrophages cultured in conditioned medium or co-cultured with cancer cells strongly suggested a positive feedback loop between TAMs and breast cancer cells." (PMID 32365569, 2020).
COVID-19 (24 papers, 2021 to 2026). A disease caused by infection with severe acute respiratory syndrome coronavirus 2. "In conclusion, MMP9, CASP1, and CAMP were identified as promising biomarkers and potential targets for therapy of post-COVID-19 GBS." (PMID 40433617, 2025). "Further studies are needed to clarify the relationship between the upregulation of CAMP expression and immune response outcomes, as well as to elucidate the pathophysiological mechanism in post-COVID-19 GBS patients." (PMID 40433617, 2025). "By searching for DTGs associated with IRGs shared between COVID-19 and IS, we identified eight DEGs interacting with two known databases of drug targets: JAK2, ORM1, RNASE2, TNFSF13B, CYBB, EIF2AK2, CD79B and CAMP." (PMID 36969251, 2023). "The COVID-19 dataset revealed CAMP (AUC: 0.692), LTF (AUC: 0.764), DEFA1B (AUC: 0.701), SAMD9(AUC: 0.786), GBP1(AUC: 0.757), DDX60 (AUC: 0.802), DEFA4 (AUC: 0.763), and OAS3(AUC: 0.801) that exhibited superior diagnostic capabilities." (PMID 38115996, 2023). "Genes associated with the immature neutrophil subset (CD24, LTF, CAMP) were up-regulated in COVID-19(+) TV skin, but not in COVID-19(+) PU or COVID-19(-) PU skin tissue." (PMID 37026002, 2023). "Employing various algorithms, we identified MMP9, CAMP, and CASP1 as NETRGs, demonstrating good discriminatory capacity in COVID-19 and GBS." (PMID 40433617, 2025). "One DEG in this category, CAMP, codify for the antimicrobial molecule cathelicidin (LL37), a modulator of TLR activation and inflammation that has been proposed as a potential candidate for COVID-19 prevention and treatment." (PMID 36650374, 2023). "The upregulation of CAMP in both COVID-19 and GBS patients was observed in our study, but it is not clear whether the positive immunomodulatory activity directly impacts disease outcomes or if the deregulation of expression leads to a negative effect." (PMID 40433617, 2025).
viral infection (24 papers, 2011 to 2025). "Furthermore, IL1A, IL12B, DEFB4A, and CAMP, which are associated with the inflammatory response and inhibition of viral infection, were significantly more abundant in the HSV-1 epithelial keratitis patients than in the healthy control subjects." (PMID 32867704, 2020). "To test whether these protein candidates would be detectable in clinical samples, we selected four proteins (IL1Α, IL12B, DEFB4A, and CAMP) for ELISA analysis based on the following criteria: abundance, repeatability, and association with viral infection." (PMID 32867704, 2020). "During viral infections, type-1 interferon (IFN), IFN-α, and IFN-β exert antiviral activity during viral infections, and CAMP/LL-37 exerts antiviral activity as well." (PMID 38396804, 2024). "Several pathogens have been shown to downregulate CAMP expression, yet it is unclear if such modulation occurs during a viral infection." (PMID 29780383, 2018). "There have been few reports on how viral infections modulate CAMP expression." (PMID 29780383, 2018). "Although type I interferon has been suggested to suppress vitamin D-dependent CAMP response in human monocytes/macrophages, to our knowledge it is still unknown if viral infections modulate CAMP expression in these cells." (PMID 29780383, 2018). "Levels of CAMP (cathelicidin antimicrobial peptide) were elevated in MIS-C in comparison with bacterial and viral infections but not KD." (PMID 39300098, 2024).
autoimmune disease (23 papers, 2014 to 2026). A disorder resulting from loss of function or tissue destruction of an organ or multiple organs, arising from humoral or cellular immune responses of the individual to their own tissue constituents. "Interestingly, the three genes (LTF, CAMP, and DEFA4, encoding lactoferrin, cathelicidin, and α-defensin 4) were closely related to immune function and autoimmune diseases." (PMID 24741625, 2014). "In autoimmune disease, such as SLE, DNA covariates with large amounts of neutrophil proteins including LL37 (a cathelicidin antimicrobial peptide) and high-mobility group box 1 (HMGB1), to activate plasmacytoid DCs (pDCs)." (PMID 35686129, 2022).
colon carcinoma (23 papers, 2013 to 2025). "CAMP exerts anti-cancer effects in colon cancer, gastric cancer, hematologic malignancies, and oral squamous cell carcinoma." (PMID 37958632, 2023). "Immunohistochemical staining of tissue arrays revealed that LL-37 is highly expressed in normal colon mucosa, while it is downregulated in colon cancer tissues because of DNA methylation in the CAMP gene promoter." (PMID 32575664, 2020). "The cathelicidin antimicrobial peptide, LL-37, induced growth suppression significantly in the colon cancer cell line HCT116 at a concentration higher than 50 μg/mL." (PMID 28061765, 2017). "According to results of reporter assay, we expected that the CpG site at −233/−232 would play important roles for transcription regulation of human CAMP in some specific cells, such as colonic cancer Caco-2 cells." (PMID 28427192, 2017). "We report that human cathelicidin antimicrobial peptide, LL-37, and its analogues suppress the proliferation of colon cancer cells via the upregulation of miR-663a abrogating CXCR4 expression." (PMID 28061765, 2017). "Increased CAMP expression in response to vitamin D3 has been shown in other cell types including acute myeloid leukaemia, immortalized keratinocyte, colon cancer cell lines, bone marrow derived macrophages and airway epithelial cells." (PMID 25089904, 2014). "Though we couldn't detect methylation of CpG site at −233/−232 of human CAMP promoter in selected epithelial cancer cell lines, we did detect full methylation of CpG site at −233/−232 human CAMP promoter in a colonic cancer cell line, Caco-2 cell." (PMID 28427192, 2017). "Conversely, the expression of the CAMP gene and LL-37 secretion levels are significantly inhibited in stomach cancer, HT-29 and HCT116 colon cancers, chronic lymphocytic leukemia, U937 lymphoma, and SH-SY5Y neuroblastoma cells." (PMID 39339270, 2024). "5-Aza-CdR but not TSA or DZNep restored CAMP gene expression in cultured colonic cancer cells." (PMID 28427192, 2017).
diabetes (19 papers, 2014 to 2025). "Of note, CAMP has previously been reported to be linked to diabetes mellitus type 1, and its circulating levels have been suggested as a marker for diabetic nephropathy." (PMID 37629082, 2023). "However, the possible impact of HIF-1 on the antimicrobial peptide LL-37, encoded by CAMP in diabetes, is not fully understood and was therefore investigated." (PMID 34651203, 2022).
lung carcinoma (17 papers, 2013 to 2025). "Recent researches indicated that CAMP/creb-regulated LINC00473 was highly expressed in LKB1-inactivated lung cancer and promoted lung cancer growth." (PMID 32878637, 2020). "CAMP signaling increases histone deacetylase 8 (HDAC8s) expression through the Epac–Rap1–Akt pathway leading to augmenting cisplatin-induced apoptosis and inhibits radiation-induced ATM phosphorylation promoting apoptosis in lung cancer." (PMID 35419410, 2022).
rheumatoid arthritis (17 papers, 2014 to 2024). A chronic, systemic autoimmune disorder characterized by inflammation in the synovial membranes and articular surfaces. "Quantitative proteomics analysis of NETs in response to PMA and A23187 in neutrophils from rheumatoid arthritis and SLE indicated PMA-induced NETs contained proteins of annexin family, azurocidin, and histone H3, whereas A23187 enriched CAMP/LL37, CRISP3, lipocalin, IL-8, and PADI4." (PMID 35622142, 2022).
asthma (16 papers, 2015 to 2025). "CAMP is released by neutrophils during inflammation to host defense, although its role in asthma has been little investigated." (PMID 38542471, 2024). "We identified a potential five-biomarker panel (BPIFA1, MUC5AC, CAMP, CTSG, and ANXA1) that illustrates the inflammatory activity of asthma in sputum and could improve asthma phenotyping, providing valuable insights into personalized treatment approaches." (PMID 38542471, 2024). "Moreover, NFATc2 mRNA showed altered expression levels in peripheral blood from 981 children and adults from the Asthma BRIDGE and CAMP cohorts." (PMID 33079489, 2020).
cystic fibrosis (16 papers, 2011 to 2025). Autosomal recessive disorder caused by pathogenic variants in the CFTR gene (cystic fibrosis transmembrane conductance regulator), which encodes a chloride and bicarbonate channel expressed in epithelial cells, and follow the diagnosis criteria. "Such experiments are frequently used to evaluate the activity of the cystic fibrosis transmembrane conductance regulator (CFTR), a cAMP‐activated chloride channel that is defective in cystic fibrosis, one of the most frequent genetic diseases." (PMID 40047394, 2025). "Synergy in augmenting CAMP expression was also observed when vitamin D-3 was combined with calcium in normal and cystic fibrosis bronchial epithelial cells." (PMID 39053604, 2024). "However, the sputum inflammatory cellular profile was investigated only in cystic fibrosis that presented higher levels of CAMP—consequently, with a high count of neutrophils." (PMID 38542471, 2024).
tuberculosis (16 papers, 2009 to 2024). A chronic, recurrent infection caused by the bacterium Mycobacterium tuberculosis. "Subsequently, the effects of vitamin D3 on AMP-expression in relation to tuberculosis (TB) and leprosy were demonstrated both in vitro and in vivo, and the anti-mycobacterial activity was dependent on the CAMP gene." (PMID 32595649, 2020). "The effects of vitamin D on the CAMP gene are well-documented and relevant for Mycobacterium infections, both leprosy and tuberculosis." (PMID 32595649, 2020). "CAMP is a vitamin D-related gene that would be triggered in response to vitamin D. It is essential for macrophages infected with MTB to benefit from the antimicrobial reaction induced by vitamin D. CAMP activation enhances the effectiveness of immune responses in tuberculosis." (PMID 34803519, 2021). "In addition, we noticed that CAMP was mainly enriched in the following signaling pathways and biological processes: tuberculosis, innate immune response, cell redox homeostasis, cellular response to interleukin-1, and cellular response to tumor necrosis factor." (PMID 33758323, 2021).
periodontitis (15 papers, 2013 to 2025). An acute or chronic inflammatory process that affects the tissues that surround and support the teeth. "HA2-FimA DNA vaccine can increase the levels of SIgA and CAMP in the saliva of experimental periodontitis model rats and reduce alveolar bone loss." (PMID 38687028, 2024). "Clear data demonstrate that exposure of gingival epithelial cells to oral bacteria that have been associated with periodontitis results in the production of an array of innate immune molecules, including β-defensins and CAMP (LL-37)." (PMID 35330821, 2022). "We have previously reported that local deficiency in hCAP-18/LL-37 and p.S34N mutation in CAMP gene, which is the gene encoding the LL-37, might be a confounding factor in the pathogenesis of generalized aggressive periodontitis." (PMID 24949444, 2014). "Among them, during weeks 12 to 15, group B (periodontitis + pVAX1-HA2-FimA group) consistently had higher levels of CAMP in saliva compared to the other groups, and the difference was statistically significant (p < 0.05)." (PMID 38687028, 2024). "The HA2-FimA DNA vaccine can increase the levels of SIgA and CAMP in an experimental rat model of periodontitis, effectively activating the immune response and reducing alveolar bone loss." (PMID 38687028, 2024). "The rat antimicrobial peptide ELISA kit results showed that the CAMP level trend in group B (periodontitis + pVAX1-HA2-FimA group) was similar to the levels of specific SIgA antibodies." (PMID 38687028, 2024). "In another study, cathepsin G, cathelicidin antimicrobial peptide, protein S100-A7, 14-3-3 protein sigma and vitamin D-binding were found more frequently in chronic periodontitis when compared to healthy subjects." (PMID 24098404, 2013). "Compared with the other three groups, the rats in the periodontitis+pVAX1-HA2-FimA vaccine group showed higher levels of SIgA and CAMP (p < 0.05)." (PMID 38687028, 2024).
pneumonia (15 papers, 2008 to 2025). An acute, acute and chronic, or chronic inflammation focally or diffusely affecting the lung parenchyma, caused by an infection in one or both of the lungs (by bacteria, viruses, fungi, or mycoplasma.). "The top 50 over-abundant transcripts in pneumonia were dominated by antimicrobial neutrophil-related genes e.g ELANE, DEFA1B, MMP8, CAMP, DEFA3, DEFA4, MPO, LTF." (PMID 23940611, 2013). "Of interest, the RNA abundance of five genes were altered by pneumonia in both the mouse and human gene sets: lactotransferrin (LTF), cathelicidin antimicrobial peptide (CAMP), phospholipid scramblase 1 (PLSCR1), inhibin beta A (INHBA), and hydroxyprostaglandin dehydrogenase 15-(NAD) (HPGD)." (PMID 18270561, 2008).